BCL2 (BCL2 apoptosis regulator)
Diseases named in the same sentence as BCL2 in open-access papers (continued):
Sharing a sentence is not in itself a finding about the gene and the disease.
glioma (continued). "Ibrutinib inhibits glioma cell growth also through the regulation of Bcl-2/Bax and activation of caspase-3." (PMID 28946903, 2017). "SAHA or/and MG132 induced apoptosis in the glioma cells was attributable to the down-regulation of Bcl-2 protein levels and the up-regulation of 14-3-3, Bax, Caspase 9, Capase 3 expression via extrinsic and intrinsic pathways." (PMID 27911270, 2017). "The knockdown of mTOR and Bcl‐2 exerted a similar effect as depletion of miR‐497 on reducing both glioma cell lines resistance to TMZ treatment." (PMID 28064447, 2017). "Through upregulation of Fas/FasL and Bax, activation of caspases, and downregulation of Bcl‐2, bELE also induced apoptosis in glioma cells." (PMID 28297578, 2017). "Our result revealed that the protein levels of IGF1R, IRS1, mTOR, and Bcl‐2 were increased in TMZ‐resistant glioma cells (U87‐TR and SF295‐TR) compared with TMZ‐sensitive glioma cells (U87 and SF295)." (PMID 28064447, 2017). "BCL2 also regulates migration, invasion and metastasis in several cancers including gliomas, squamous cell carcinoma, neuroblastoma, lung and colorectal cancer." (PMID 28340489, 2017). "Sch B induces cell apoptosis by increasing Bax, cleaved caspase-9, cleaved caspase-3, and cleaved PARP and reducing Bcl-2 protein expression in glioma cells." (PMID 25685066, 2015). "MiR-153 is significantly down-regulated in glioma compared with normal brain tissues and decreases cell proliferation and increases apoptosis by targeting B cell lymphoma 2 (Bcl-2) and myeloid cell leukemia sequence 1 (Mcl-1) genes in glioma cell lines." (PMID 26124081, 2015). "Several studies have documented a role for miR-21 in protecting glioma cells from chemotherapy drugs via regulation of Bcl-2 and caspase-3 activity." (PMID 26473373, 2015). "The aim of this study was to investigate the mechanisms and effects of B-cell lymphoma 2 (Bcl-2) on the vasculogenic mimicry (VM) of human glioma cells." (PMID 25667663, 2015). "In this study we also detect the expression of Bcl-2 to further certify the effect of saw palmetto on the glioma cell." (PMID 26788112, 2015). "The inhibited DKK2 expression lead to up-regulation of the protein levels of Bcl2 and c-Myc in glioma cells." (PMID 26656471, 2015). "Of note, miR-34a expression was downregulated on our initial oncomir microarray, inversely correlated with miR-10b as it has been reported to be with Bcl-2 expression in gliomas." (PMID 26394044, 2015). "Bcl2 is an anti-apoptotic mitochondrial protein, and can provide resistance to cell death when transfected into a glioma cell line." (PMID 24847208, 2014). "Reduced PAX8 expression produced a reduction in the BCL2 expression levels, and BCL2 inhibition by siRNA-knockdown reduced the glioma cell growth rate." (PMID 24602166, 2014). "For example, MiR-34 inhibits human pancreatic CSCs by regulating Notch and bcl-2 gene expression, and miRNA-34a suppresses glioma CSC growth by targeting several oncogenes." (PMID 24823879, 2014). "Overexpression of miR-181b reduced chemoresistance to temozolomide in glioma stem cells by targeting Bcl-2." (PMID 24788655, 2014). "In revealing the anti-apoptotic mechanism of ATF5 in HCMV-infected glioma, it was found that Bcl-2 was downregulated in the U87 cells in which ATF5 was inhibited, when compared with the control." (PMID 25120656, 2014).
glioma (continued). "For instance, CD133+ glioma CSCs express a high level of anti-apoptotic proteins Bcl-2 and Bcl-XL, and high expression of Mcl-1 correlates with resistance to the Bcl-2 inhibitor ABT-737 in glioma CSCs." (PMID 24823879, 2014). "Daidzein reverses TRAIL-resistance in LNCaP prostate cancer stimulating the decrease in the MMP and in LN229 glioma cells activating caspase-9 and downregulating of bcl-2." (PMID 23573148, 2013). "MiR-181a also downregulates Bcl-2 and significantly sensitizes malignant glioma cells to radiation treatment." (PMID 24202447, 2013). "We conclude that metabolic therapy in pediatric high grade glioma is greatly enhanced by impairment of BCL-2/BCL-xL function, and that future therapies should be developed based on this approach." (PMID 23691145, 2013). "In human gastric carcinoma cells and rat glioma cells, SW induces apoptosis by involving Ca2+ overload and Bcl-2 expression decrease." (PMID 24124558, 2013). "Similar with the results of glioma cells, shikonin or topotecan significantly reduced the expression of Bcl-2 as well as promoted the activation of caspase-9 and caspase-3 in GSCs-U251 and GSCs-U87 cells respectively, compared to the control groups (P<0.01)." (PMID 24303074, 2013). "Further detailed studies are required in order to determine how ABT-263 promotes apoptosis in response to agents targeting tumour metabolism and how these agents affect the balance of pro and anti-apoptotic BCL-2 proteins in pediatric glioma cells." (PMID 23691145, 2013). "In glioma cells, HuR regulates B-cell lymphoma 2 (BCL2) expression through its 3′UTR during chemotherapeutic agent-induced apoptosis." (PMID 23965981, 2013). "In contrast, HuR overexpression resulted in chemoresistance to standard glioma therapeutic agents such as etoposide, topotecan, and cisplatin by stabilizing BCL2 mRNA as well as enhancing translational efficiency." (PMID 23965981, 2013). "Our data also demonstrates that combined inhibition of glycolysis and BCL-2/BCL-xL function effectively promotes cell death in response to metformin treatment in pediatric glioma cells." (PMID 23691145, 2013). "Although BCL2 at low expression levels in gliomas is antiapoptotic, high levels of BCL2 facilitate FASLG-mediated apoptosis in this cancer type." (PMID 23777485, 2013). "H2O2 induces autophagy through interference with the beclin-1 and Akt/mTOR signaling pathways, and is regulated by the anti-apoptotic gene Bcl-2 in glioma U251 cells." (PMID 22363680, 2012). "Here, we observed a decrease in Bcl-2 expression in glioma cells subjected to TMZ-Se treatment, indicating that the decrease of Beclin 1 leads to the dissociation of Beclin1 with Bcl-2, thereby promoting the degradation of Bcl-2 and causing apoptosis." (PMID 22496897, 2012). "HA-14-1 and ABT-737, which are the most potent BH3 mimetic with high affinity (Ki ≤ 1) to Bcl-2, Bcl-xL, and Bcl-w, induce apoptosis in glioma cell lines by promoting the release of proapoptotic Bax from a Bax:Bcl-2 heterodimeric complex." (PMID 22431925, 2012). "WP1066 selectively inhibits the STAT3 pathway and reduces STAT3-driven expression of Bcl-2, Bcl-xL, and Mcl-1, triggering Bax activation and resulting in extended survival of xenogeneic glioma mouse models." (PMID 22431925, 2012). "In glioma SCs, high levels of Bcl-2 and Bcl-XL have been detected in the CD133+ subpopulation compared with the CD133- fraction." (PMID 24212789, 2011). "Western blot analysis revealed that the changes of survivin, Bcl-XL, Bcl-2, and Mcl-1 protein in C6 glioma cells treated with 10 μmol/L of LY294002, or/and 5 μmol/L of tamoxifen for 24 h were similar as the changes of mRNA." (PMID 22046442, 2011). "Both the high levels of miR-17 and miR-20a and the low level of miR-139-5p that putatively target BCL2 are therefore consistent with the high level of BCL2 we observed in gliomas and are related to an expected antiapoptotic effect." (PMID 21655185, 2011).
glioma (continued). "Upon BPA-BNCT treatment, the Bax level increased in glioma cells, whereas Bcl-2 expression decreased." (PMID 21122152, 2010). "It has been reported that BA enhanced the levels of BAX and BCL-2 proteins in glioma cells and induced apoptosis in those cells." (PMID 15083202, 2004). "The rat glioma cell line A15A5 was stably transfected with human Bcl-2 and Bax transgenes and the viability of theses cell lines was analyzed in vitro and in vivo." (PMID 15331018, 2004). "Nevertheless, these results suggest that human Bax and Bcl-2 transgenes were functional in the rat glioma A15A5 cells." (PMID 15331018, 2004). "This study of 187 high grade gliomas reviews clinicopathological prognostic features and the relationship to bcl-2 expression." (PMID 12085183, 2002). "Hyperphosphorylated Akt correlates with aggressive glioma biology, enhanced temozolomide and radiotherapy resistance, and suppression of apoptosis through inhibition of caspase-9 and stabilisation of anti-apoptotic Bcl-2." (PMID 41511337, 2025). "The interaction between beclin-1 and Bcl-2 proteins may represent a key molecular switch that controls whether glioma cells undergo survival or death." (PMID 41511337, 2025). "Although direct glioma-specific evidence linking PLCγ1/PKC-mediated phosphorylation to disruption of the Bcl-2:beclin-1 complex is limited, existing studies demonstrate that PLCγ1-driven Ca2+ flux modulates autophagy-apoptosis balance by influencing beclin-1 availability at the ER membrane." (PMID 41511337, 2025). "Studies suggest that inhibiting BCL6 and BCL2 expression may serve as a therapeutic target for central nervous system cancer." (PMID 40520536, 2025). "Some studies revealed that gliomas might express high levels of Bcl-2 protein, possibly enabling GBM cells to resist and evade apoptosis." (PMID 38698968, 2024). "Additionally, miR-153-3p has been shown to enhance cell radiosensitivity in human glioma by targeting BCL2." (PMID 38843497, 2024). "In addition, changes of Bax and Bcl-2 expression in glioma cells were further verified by western blotting and qRT-PCR." (PMID 38730506, 2024). "For example, in glioma cells, miR-30c-5p could induce apoptosis and inhibit growth and invasion by targeting Bcl2, suggesting its potential as a therapeutic target to improve overall patient survival in glioma." (PMID 39777350, 2024). "Furthermore, DET modulates apoptosis in glioma cells by downregulating BCL2 expression while simultaneously upregulating BAX expression." (PMID 39850823, 2024). "In addition, recent evidence showed that 5-LOX can contribute to a proliferative and pro-survival effect in glioma cells through a modulation of ERKs phosphorylation, Bcl-2/Bax signalling and via β-catenin-dependent pathway." (PMID 38816839, 2024). "Apigenin and arctiin at a dose of 0–50 μM reduce cell migration, invasion leading to apoptosis and cell death increasing CDK‐Cyclin mediated G2/M phase cell cycle of the G2/M phase mediated by CDK‐Cyclin, generating ROS and the Bax/Bcl‐2 ratio in the invitro technique inin the glioma U87 cell line." (PMID 37675821, 2023). "The results of this research showed that the usage of the intracellular survival signaling pathway inhibitors PI3K-Akt/PKB-mTOR and Ras-Raf-MEK-ERK in simultaneous application resulted in the formation of Bcl-2 and beclin-1 complexes, which was correlated with induction of apoptosis in glioma cells." (PMID 38067099, 2023). "Indeed, curcumin was reported to sensitise glioma cells to doxorubicin by inhibiting the expression of BCL-2 and IAP family members and DNA repair enzymes." (PMID 37628772, 2023). "In glioma cells, treatment with TEA significantly increased the number of reactive oxygen species (ROS) and altered B-cell lymphoma protein 2/B-cell lymphoma protein-associated X (Bcl-2/Bax) balance, which further resulted in cell apoptosis." (PMID 37367787, 2023).
glioma (continued). "Therefore, the aim of the present study was to investigate, for the first time, the role of Bcl-2:beclin-1 in “switching” between apoptosis and autophagy in glioma cells using the combined action of LY294002 and sorafenib." (PMID 38067099, 2023). "Therefore, we examined the expression of apoptosis-related proteins such as BAX and Bcl-2 in AKR1B1-expressing glioma cells." (PMID 37185746, 2023). "Bone marrow-derived MSCs not only promote apoptosis and inhibit proliferation of glioma U251 cells via up-regulation of the IL-12 and IFN-γ levels and Bax/Bcl-2 expressions in tumor cells, but also restrict angiogenesis in ΔGli36 glioma xenograft via downregulation of the PDGF/PDGFR axis." (PMID 37237420, 2023). "Bcl2 is an oncogenic and antiapoptotic mitochondrial protein involved in glioma development." (PMID 37509289, 2023). "Moreover, the miR-424/AKT3 axis plays roles in glioma progression and invasion by altering the expression of cyclinD1, c-Myc, Bax, and Bcl-2." (PMID 37998329, 2023). "Equol prevents LPS activity, induces TLR4 activation and JNK phosphorylation, upregulates the expression of Bax and cleaved caspase‐3, downregulates the expression of Bcl‐2, and, when administered at a specific dose of 20 μM, increases apoptosis and neuronal death in vitro glioma cell line C6." (PMID 37675821, 2023). "On the other hand, it has been proposed that Beclin1 could show a pro-apoptotic effect by preventing of function of Bcl-2 and BclxL in glioma cells." (PMID 38139462, 2023). "Daidzein induces the arrest in the cell cycle, while it lowers the cells proliferation in glioma cell U87M, U251, U‐118MG, and A‐172 at a dose of 0–20, 40, and 80 μM, respectively, by downregulating the expression of Bcl‐2 and CD44/moesin /β‐catenin signaling pathway in vitro manner." (PMID 37675821, 2023). "Also in this case, curcumin was able to sensitise glioma cells to cisplatin by decreasing the expression of BCL-2 and members of the IAP family, as well as DNA repair enzymes." (PMID 37628772, 2023). "Expanding knowledge of the central nervous system tumors, such as malignant gliomas, based on the role of the molecular switch, the Bcl-2:beclin-1 complex may be the basis of modern anticancer therapy development." (PMID 38067099, 2023). "Andrographolide can also inhibit the growth, migration, and apoptosis of human glioma u87-MG cells by up-regulating the expression of apoptosis-related proteins caspase-3, Bax, and PARP and down-regulating the expression of anti-apoptotic protein Bcl-2, thereby exerting its anti-glioma activity." (PMID 36177361, 2022). "Unlike aspirin and indomethacin, which have an effect on Bcl-2, Mcl-1, and Noxa, Noxa appeared to be a susceptible Bcl-2 family protein upregulated by dipyridamole which contributed to glioma apoptosis." (PMID 35054765, 2022). "MiR-873 mediates cisplatin resistance in glioma cells by increasing the protein level of Bcl-2." (PMID 35674307, 2022). "Therefore, the cRGD-P/ARV-DOX micelles promoted apoptosis of glioma cells by activating the caspase cascade, down-regulating Bcl-2 expression and up-regulating BAX expression." (PMID 36157053, 2022). "To analyze whether inhibition of anti-apoptotic Bcl-2 proteins is sufficient to induce glioma cell death, we used two different BH3 mimetics, Hyp and Goss, in this study." (PMID 36267274, 2022). "In addition, interleukin-24 (IL-24) in glioma cells affects the sensitivity of gliomas to cisplatin by regulating the expression levels of P-gp and Bcl-2." (PMID 35674307, 2022). "Hence, PSMC2 plays a role in the apoptosis of glioma by acting on the Bcl-2/Bax/cleaved caspase-3 apoptosis signaling pathway." (PMID 35287689, 2022). "In addition, the expression of miR-873 was down-regulated while the expression of B-cell lymphoma 2 (Bcl-2) was up-regulated in glioma tissues compared with normal brain tissues." (PMID 35674307, 2022). "BAD and Bcl-2 are also potential target of wogonin in glioma." (PMID 36618921, 2022).
glioma (continued). "miR-30c targets Bcl-2 and activates the caspase pathway in glioma cells." (PMID 36180477, 2022). "The overexpression of BRD4 in cancer cells can induce abnormal expression of its downstream genes involving some pivotal oncogenes such as c-Myc and Bcl-2, which contributes to the occurrence and development of glioma, acute myeloid lymphoma (AML), breast cancer, and other tumors." (PMID 36157053, 2022). "In addition, we explored the effects of these compounds on the viability of human glioma U87 MG cells and on the expression levels of Bcl-2 and Mcl-1 proteins." (PMID 36267274, 2022). "Similarly, lncRNA LOC101928963 inhibited PMAIP1 expression, which also induced bcl-2 and reduced bax expression, and ultimately inhibited the apoptosis of glioma." (PMID 35912271, 2022). "Also, PTX was capable of activating caspase-3 (the effector of apoptosis pathways) and reducing Bcl-2 expression (the anti-apoptotic protein) to repress glioma cell apoptosis, which was partially consistent with our findings." (PMID 34261493, 2021). "We discovered that LINC01087 was also highly expressed in glioma through GEO (gene expression omnibus) chip analysis, and predicted that it might mediate miR-384/Bcl-2 axis to take part in the development of glioma." (PMID 34459789, 2021). "Reduced Bcl-2 expression and elevated expression of Caspase-3 and Bax have been used previously as indicators of induced apoptosis of glioma cells and desirable oncologic outcomes of patients with glioma following radiotherapy and/or chemotherapy." (PMID 34261493, 2021). "Similarly, the combined treatment (As+Cd+Pb) in individual lethal concentration (LC)-5 induced a toxic effect on C6-glioma cells derived from rat glioma, via mitochondria-mediated apoptosis, including caspase-9 activation and Bax/Bcl-2 changes." (PMID 34204190, 2021). "In U251 glioma cells, we found that Bcl2 is localized mainly in the ER and is translocated to MAM and mitochondria upon induction of apoptosis; this mitochondrial transfer was not restricted to the demonstrator cell line, even if cell-specific modulations exist." (PMID 33589622, 2021). "In glioma cells, GLIPR1 overexpression reduced c-Jun N-terminal kinase (JNK) phosphorylation and induced Bcl-2 expression, thus increasing cell survival and glioma cells’ protective effect against apoptotic stimuli such as Fas ligation, chemotherapy, and radiation treatment." (PMID 34142021, 2021). "In addition, analysis of luciferase assay confirmed that Bcl-2 was a direct target of miR-873 and showed that miR-873 negatively correlated with Bcl-2 reduction in cisplatin-resistant glioma cells." (PMID 34065991, 2021). "Upregulated expression of CRNDE induces EGFR (epidermal growth factor receptor) activation, resulting in apoptosis inhibition through an increased Bcl2 (B-cell CLL/lymphoma 2)/Bax (BCL2-associated X) ratio and an association with poor survival in glioma patients." (PMID 34316694, 2021). "In-depth studies of glioma have revealed a close correlation of bcl-2 and bax with cell apoptosis." (PMID 34556140, 2021). "This suggested that LINC01087 could take part in glioma growth through miR-384/Bcl-2 axis (*P < 0.05)." (PMID 34459789, 2021). "The results indicated that the fluorescence activity of Bcl-2-WT could be inhibited by miR-384-agomiR, and the Bcl-2 mRNA and protein expression in glioma cells transfected with miR-384-agomiR was obviously inhibited." (PMID 34459789, 2021). "Furthermore, in the present study, the combined treatment of chemotherapy-hyperthermia caused an upregulation of Cleaved Caspase-3 and Bax while downregulating Bcl-2, in contribution to glioma cell apoptosis, which was further enhanced by RGE embellishment." (PMID 34261493, 2021).